CD38 (CD38 molecule)
Diseases named in the same sentence as CD38 in open-access papers (continued):
Sharing a sentence is not in itself a finding about the gene and the disease.
tumor (continued). "We present in this paper that inhibition of the enzyme activity of CD38 on human T cells protects NSG mice against Graft-versus-Host Disease (GvHD) while leaving the Graft-versus-Tumor (GvT) response intact." (PMID 41159029, 2025). "Over 21 days, tumour growth was slower in the EVs‐DoxMNs and CD38‐EVs‐DoxMNs groups compared to the i.v groups." (PMID 40317915, 2025). "Studies have shown that elevated CD38 expression on Teffs affects mitochondrial metabolism and, thereby, their functionality at the tumor site." (PMID 40117361, 2025). "Subsequent pharmacodynamic and immunodepletion studies underscore the innate and adaptive immune effects of a CD38-directed AttenukineTM in driving these anti-tumor responses." (PMID 40315226, 2025). "A central advantage of nanobodies as easily interchangeable tumor binding modules is the option to generate biparatopic CD38-specific BARs by combining two CD38-specific nanobodies in a single BAR." (PMID 41254160, 2025). "The depletion of NAD+ by CD38 activity not only alters intracellular energy homeostasis but also reshapes the extracellular metabolite milieu within the tumor microenvironment." (PMID 40361394, 2025). "The inclusion of CD38 can further aid in recognizing disease progression stages, assessing patient prognosis, and helping clinicians better evaluate the tumor burden." (PMID 39996780, 2025). "CD38‐EVsMNs exhibited the highest fluorescence intensity among all groups, with fluorescence microscopy of tumour tissue sections 3 h post‐treatment further confirming the most robust PKH‐26 staining in the CD38‐EVsMNs group." (PMID 40317915, 2025). "Blocking CD36-mediated lipid uptake on cytotoxic CD38+ T-cells or Tregs enhances anti-tumor immune response(s)." (PMID 40563926, 2025). "For instance, in hypoxic tumor microenvironments, CD38 enzymatic function fosters an immunosuppressive milieu." (PMID 40721446, 2025). "Overexpression of CD38 in the tumor microenvironment (TME) fosters immune suppression by reducing cytotoxic T-cell activity." (PMID 40458726, 2025). "Taken together, these data point to a dual mechanism of action for a CD38-targeted AttenukineTM, involving both immune and tumor-directed activity, and highlight the potential benefit of a CD38-targeted attenuated IFNα therapy." (PMID 40315226, 2025). "We observed that the frequency of CD38-expressing CD8+ T cells was ~threefold to fourfold more abundant at the tumor site than the spleen." (PMID 38451948, 2024). "AMG424 has demonstrated strong anti-tumor activity in vitro against MM cell lines with both low and high expression levels of CD38." (PMID 38961036, 2024). "A recent study has revealed that a heightened level of CD38 expression in TILs promotes increases in the levels of Ki-67 in tumor cells, and that highly expressed CD38+ TILs independently predict shorter OS and PFS." (PMID 38404585, 2024). "[68Ga]Ga‐AJ206 PET showed specific accumulation of radioactivity in both the PDXs that reflected the CD38 expression detected by flow cytometry pre‐ inoculation and by IHC of the tumor sections." (PMID 38421139, 2024). "Deletion of CD38 in human primary NK cells eliminates Dara-mediated fratricide and enhances the anti-tumor activity of NK cells." (PMID 38355622, 2024). "The in vivo experiments consistently demonstrated that inhibiting the enzymatic activity of CD38 or blocking its enzymatic product led to similar inhibitory effects on tumor proliferation and metastasis, comparable to CD38 gene knockout or mutation." (PMID 38533509, 2024). "Akin to the B16-F10 tumor model, CD38-expressing CD8+ T cells were highly abundant at the tumor site and were characterized by the co-expression of PD1 and Tim3, elevated expression of Tox, and reduced TCF1 levels." (PMID 38451948, 2024). "We then performed mIHC staining in these tumor sections to analyze the co-localization of PD-1, CD38 and CD8, and further compare the expression of CD38 and PD-1 on CD8+ cells across different patient groups." (PMID 39726591, 2024).
tumor (continued). "As seen for similar modalities against other targets, efficacy of these novel agents, in addition to mAbs, is likely to also be affected by CD38 antigen density on tumor cells." (PMID 40453054, 2024). "In the present study, we demonstrated that lactate, which is derived from tumor metabolism remodeling, upregulates the expression of CD38 through OXPHOS‐driven Hippo‐TAZ pathway." (PMID 38545257, 2024). "These cells are associated with the inflammatory response and are implicated in multiple negatively regulated pathways that can facilitate the invasion and metastasis of tumor cells; in THn, CD38, NCF4, CRTAM, etc. are highly expressed." (PMID 39452125, 2024). "A combination of low affinity CD138 CAR containing a stimulatory domain with a high affinity CD38 costimulatory CAR was shown to effectively differentiate between tumor and normal tissues." (PMID 39606234, 2024). "Recently, a trispecific antibody that interacts with CD38 on tumor cells and CD3 and CD28 on T cells displayed enhanced cytotoxicity to tumor cells." (PMID 38672132, 2024). "Our findings in the present study also confirmed that high levels of CD38+CD8+ T cells are indicative of incomplete tumor response in patients with HCC treated with TACE with or without the administration of PD-1 inhibitors." (PMID 38404585, 2024). "In Daudi cells and L-1236 cells, IMM5605–26B4 and IMM5605–35G5 inhibited CD38 enzymatic activity, which is responsible for immunosuppressive adenosine production in the tumor microenvironment." (PMID 38983860, 2024). "Conversely, a more activated immune environment dominated by CD38 pos NK cells, experiences major NK cells depletion after daratumumab, limiting subsequent anti-tumor activity." (PMID 39030183, 2024). "First, we evaluated the abundance of tumor antigen-experienced (CD44hi) CD38-expressing CD8+ T cells in the tumor-bearing host when the tumor size reached ~100 to 120 mm2 (between day 14 and day 15)." (PMID 38451948, 2024). "In immune cells, inhibiting CD38 expression on T cells enhanced their anti-tumor effect through the CD38-NAD+ axis." (PMID 38463232, 2024). "A combination of cisplatin/etoposide, ICB, and CD38 blockade delayed tumor growth compared to cisplatin/etoposide." (PMID 38533509, 2024). "The study also utilized the Tumor Immune Estimation Resource (TIMER) and cBioPortal databases to examine CD38 levels in various tumors and their correlation with the tumor immune microenvironment in HNSCC." (PMID 39192980, 2024). "TE‐1146 delivered the desired toxicity to tumor cells by tightly binding to CD38 on the MM cell surface." (PMID 38477561, 2024). "The upregulated genes in PTCL‐TBX21 included Th1‐related genes, including CXCR3, CD38, INFG, CXCL9, CXCL11, IL27, and genes associated with tumor immunity, such as CD274 (PD‐L1), LAG3, and IDO1." (PMID 38234210, 2024). "The tumor-bearing mice were sacrificed, femur bones extracted, and immunohistochemistry performed to demonstrate in vivo presence of CD38 + MM tumor burden." (PMID 38480650, 2024). "Expression of CD38 has also been reported in intratumoral T cells exhibiting impaired anti-tumor response." (PMID 38451948, 2024). "NAD+ modulates calcium signaling through SARM1 and CD38 in tumor progression, inflammation, and neurodegeneration." (PMID 39766263, 2024). "Poor prognosis correlates with low macrophage MHC II, high CD38 expression in the tumor microenvironment, and high CD206." (PMID 38542481, 2024). "The univariate analysis revealed that several factors were associated with LNM, including histologic grade (G2), tumor size (≥3cm), depth of invasion (T3-T4), perineural invasion, LVI, CEA and high proportion of CD38+ NK cells." (PMID 38463232, 2024). "The knockdown of Tcf7 not only weakened the anti-tumor potential of Pmel-CD38−/− T cells but also compromised their responsiveness to anti-PD1 therapy." (PMID 38451948, 2024).
tumor (continued). "A significant increase in radioactivity uptake in tumors in mice were observed following treatment with ATRA compared to pre‐treatment, and confirmed by CD38 IHC of tumor sections taken from vehicle and ATRA treated tumors." (PMID 38421139, 2024). "The immunohistochemistry (IHC) staining of the tumor lesion revealed a high expression of CD38 and PD-L1 proteins." (PMID 39000399, 2024). "Overall, research on IgD- CD38+ B cells is still limited at present, and further in-depth study is required to fully understand its function and role in tumorigenesis and tumor immunity." (PMID 38826800, 2024). "ATRA can also increase the expression of CD38 expressed by tumor cells, thus improving the efficacy of daratumumab and CD38-CART." (PMID 39027338, 2024). "The NCI-H929 tumor xenograft model was used to evaluate the efficacy of the CD38/CD47 BsAbs, including IMM5605-ISA, IMM5605-DARA, IMM5605–4A8, 12C10, 26B4, 35G5, and 65A7." (PMID 38983860, 2024). "The strongest hits in this prior study included the transcription factors STAT1 and STAT3, demonstrating a role for JAK-STAT signaling in regulating tumor CD38 expression within the bone marrow microenvironment." (PMID 40453054, 2024). "The CXCR6+ subset exhibited high levels of the exhaustion marker CD39 along with variable levels of the activation marker CD38, being more prevalent in tumor cells." (PMID 39123475, 2024). "These can be utilized for effective tumor treatment by transfusing specific T or NK cells capable of recognizing and attacking CD38+ tumor cells." (PMID 39492834, 2024). "This choice was driven by its high affinity for binding and activating FcγRs, leading to the potent induction of ADCP and ADCC against CD38+ tumor cells." (PMID 38983860, 2024). "Experimental findings indicate that Dar with a density of 4.4, named Dar4.4-IPs-VCR, exhibits the most potent anti-tumor activity against CD38-positive LP-1 MM cells." (PMID 39065683, 2024). "Genetic ablation of CD38 in tumor-reactive CD8+ T cells restored TCF1 levels and improved the responsiveness to anti-PD1 therapy in mice." (PMID 38451948, 2024). "Our BsAbs presented potent dose-dependent ADCC activity against CD47+/CD38+ Raji and NCI-H929 cells but negligible ADCC activity against CD47+/CD38– HL-60 cells, indicating low off-tumor toxicity." (PMID 38983860, 2024). "CD38 was found ubiquitously in tumor cells (TCs), fibroblast-like cells (FLCs), and tumor-infiltrating lymphocytes (TILs)." (PMID 39192980, 2024). "In a high CD38+ expressing model, the authors were able to demonstrate a significantly increased anti-tumour effect with the [177Lu]Lu-CD38 compared to the [177Lu]Lu-Ig irrelevant." (PMID 39498075, 2024). "XBP1 also showed strong positive correlations with CD38 in 2 other patient tumor gene expression data sets." (PMID 40453054, 2024). "The CD38 expression profile of the tumor cell lines was analyzed using the anti-CD38 mouse IgG1 antibody 26B4." (PMID 38983860, 2024). "Daratumumab, a human IgG1κ mAb, targets CD38's two β chains with high specificity for malignant tumor cells." (PMID 39492834, 2024). "Taken together, this study describes that the lactate‐induced CD38 enhances our understanding of the dynamic relationship between metabolism and tumor development." (PMID 38545257, 2024). "Lactic acid derived from tumor metabolic reprogramming upregulates the expression of CD38 through the OXPHOS‐driven Hippo‐TAZ pathway, promoting the conversion of nicotinamide adenine dinucleotide (NAD+) to adenosine and activating adenosine receptors." (PMID 38545257, 2024). "As expected, both CD38 pos tumor and normal cells were rapidly depleted after exposure to daratumumab." (PMID 39030183, 2024). "Several small molecules have been found to increase tumor surface CD38, with the goal of boosting mAb efficacy in a cotreatment strategy." (PMID 40453054, 2024).
tumor (continued). "64Cu-NODAGA-PEG4-SL022-GGS accumulation in the bones of tumor-naïve animals was expected and was likely due to the normal expression of CD38 by the cells of hematopoietic lineage present in the bone marrow." (PMID 38480650, 2024). "The CD38/CD47 BsAbs had a greater ability to block the CD47/SIRPα signal in CD38+/CD47+ tumor cells than IMM01 (SIRPα Fc fusion protein)." (PMID 38983860, 2024). "Previous papers reported that the roles of CD38 in immunosuppression, chemoresistance and tumor relapse." (PMID 38533509, 2024). "It effectively targets human CD38 to concentrate lenalidomide in MM cells, producing a robust anti‐cancer effect at the tumor site." (PMID 38477561, 2024). "Further exploration can be conducted on the role of CD38+ NK cells in modulating T-cell immune balance in blood and tumor microenvironment (TME) of CRC patients." (PMID 38463232, 2024). "CD38/CD47 BsAbs (IMM5605) can inhibit tumor growth via ADCC and ADCP in xenograft CB17-SICD mouse models." (PMID 38983860, 2024). "Plasma cells are specialized antibody-secreting, terminally differentiated CD38+ B cells that are components of tumor inflammatory infiltrates." (PMID 39575432, 2024). "In contrast, Pmel-CD38−/− T cells induced a robust anti-tumor response, which was further boosted upon anti-PD1 therapy." (PMID 38451948, 2024). "Daratumumab binding to CD38 on tumor cells induces complement-dependent cytotoxicity, antibody-dependent cellular cytotoxicity and phagocytosis, tumor cell apoptosis, and CD38 enzymatic activity regulation." (PMID 39046511, 2024). "We cultured hHSCs (Lin- CD34+ CD38lo/-) together with CD38+ tumor cell line or CD38+ progenitors and found that inhibition of CD38 enzymatic activity by 78c inhibitor led to the cell cycle entrance of hHSCs." (PMID 38422172, 2024). "APDCs Targeting CD38 ADCs targeting CD38 have been developed, combining targeted antibodies with cytotoxic drugs, exhibiting potent anti-tumor activity." (PMID 39065683, 2024). "CD38, a member of the ribosyl cyclase family, is expressed on various hematological cells and is known to contribute to immunosuppression and tumor promotion." (PMID 39192980, 2024). "VIS832 has also demonstrated efficacy in killing tumor cells that are resistant to daratumumab, another monoclonal antibody that targets CD38." (PMID 38961036, 2024). "MOR202 is a fully human CD38 antibody that primarily induces tumor cell lysis through ADCC and ADCP mechanisms, demonstrating promising therapeutic efficacy in clinical trials for RRMM at stage I/IIa." (PMID 39492834, 2024). "Significantly higher tracer uptake was demonstrated in tumor-bearing skeletal tissues such as spine, pelvis, and legs even though CD38 was known to be expressed at low levels in various tissues." (PMID 38480650, 2024). "Evidence of daratumumab targeting CD38 was detected in circulating immune cells and within the tumor microenvironment of mRCC and MIBC." (PMID 39207194, 2024). "These ADCs aim to deliver cytotoxic payloads specifically to CD38-expressing cells, thereby inhibiting tumor growth and inducing cell death." (PMID 38961036, 2024). "The primary mechanism of action of ATRA in the treatment of lymphoid system tumors is to increase the expression of CD38 on the surface of tumor cells, thereby increasing the efficacy of daratumumab or CD38-CART." (PMID 39027338, 2024). "It is shown that TE‐1146 remains intact and effectively enters CD38‐expressing tumor cells, releasing lenalidomide, leading to enhanced cell‐killing effects compared to lenalidomide/daratumumab alone or their combination." (PMID 38477561, 2024). "Other genes were modulated in a different way in all three SCCs (NMNAT1, NMNAT2, NADSYN1, SIRT3, and CD38) or in two tumor types (NNMT, NMNAT3, ENPP2, PNP, and SIRT1)." (PMID 38254798, 2024). "All anti-CD38 antibodies bind to CD38+ tumor cells and kill tumor cells via antibody-dependent cellular cytotoxicity (ADCC) and antibody-dependent cellular phagocytosis (ADCP)." (PMID 38983860, 2024).
tumor (continued). "The results of the flow cytometry assays showed that all anti-CD38 antibodies bound to cells in various CD38+ tumor cell lines in a concentration-dependent manner; 35G5 and 25B5 exhibited a stronger binding ability." (PMID 38983860, 2024). "In mRCC tumor tissue, a trend of decreased density of CD38-expressing cells was observed with post–daratumumab treatment." (PMID 39207194, 2024). "Two anti-CD38 antibodies engineered for linkage to anti-tumor toxins are TAK-169, which has shown promising results in preclinical research, and MT-0169, for which a Phase I dose-escalation study (NCT04017130) suggested possible utility in extramedullary MM." (PMID 39272790, 2024). "Further, low ADCC and upregulation of complement inhibitory receptors constitute part of the tumor escape mechanisms by MM cells in patients treated with anti-CD38 mAbs6." (PMID 38448430, 2024). "Treatment with daratumumab resulted in CD38-expressing immune cell subsets to be targeted both in circulation and within the tumor microenvironment." (PMID 39207194, 2024). "As such, we observed the potential of [68Ga]Ga‐AJ206 to detect varying CD38 levels in a variety of tumor models that is corroborated by CD38 IHC." (PMID 38421139, 2024). "It was found that CD38 upregulation in tumor cells produces significant NAD+ depletion, impairing mitochondrial fitness and provoking oxidative stress." (PMID 39766263, 2024). "While the Tumor_2 had relative mild cancer hallmark signatures but expressed genes associated with tumor survival signal and drug resistance (IL32, TOX2, AIF1, AKAP12, CD38 etc.), and eventually became the main tumor subtype post-treatment." (PMID 36417130, 2023). "CD38 is an immunomodulating protein that is expressed constitutively on natural killer (NK) cells and other immune cells in the tumor microenvironment (TME)." (PMID 36845935, 2023). "The strength of our retrospective study is that we showed a positive prognostic impact of CD38- and IgκC-positive tumor-infiltrating plasma cells in TNBC patients." (PMID 37894900, 2023). "Herein, we primarily focused on four important immune checkpoints viz PD1, Tim3, CD38 and Lag3, which have frequently been reported to be expressed on tumor infiltrating T cells." (PMID 37566017, 2023). "We have previously shown that CD38 is widely expressed on tumor-infiltrating leukocytes (TILs), predominantly on CD3+ T cells and monocytes." (PMID 37377962, 2023). "In the present study, through integrated bioinformatic analysis, we analyzed the expression of CD38 in head and neck squamous cell carcinoma, its survival correlation, and its effect on the immune microenvironment in multiple tumor biological databases." (PMID 36605482, 2023). "It is possible that 14 penetrates into cells, where inhibition of CD38 would only marginally affect ADO levels in the tumor microenvironment." (PMID 36845935, 2023). "CD38 expression on tumor cells was reported to rise in murine and human origins in response to PD-L1 antibody therapy, which led to dysfunction of tumor-infiltrating CD8 T cells due to increasing adenosine production." (PMID 36845744, 2023). "Most recently, innovative radiopharmaceuticals such as C-X-C chemokine receptor type 4–targeted small molecules and anti-CD38 radiolabeled antibodies have shown promising results for tumor phenotype imaging and as potential theranostics." (PMID 37591548, 2023). "JAM3, LIF, CD38, and SIGGIR, upregulated in our study, exert angiogenic and tumor-promoting effects and are linked to unfavorable cancer prognosis." (PMID 37762335, 2023). "Previously, our group found that IHC scoring of CD38+ and CD38+CD68+ cell densities in the tumor microenvironment predicted HCC patient responses to anti-PD-1/anti-PD-L1 ICB." (PMID 37342338, 2023). "The combination of C2 and additional therapeutic mAbs, such as type II anti-CD20/CD22/CD38 samples, can overcome complement attack resistance in tumor cells." (PMID 37071001, 2023).